SELENOP (selenoprotein P)
Diseases named in the same sentence as SELENOP in open-access papers (continued):
Sharing a sentence is not in itself a finding about the gene and the disease.
psoriasis (2 papers, 2020 to 2021). An autoimmune condition characterized by red, well-delineated plaques with silvery scales that are usually on the extensor surfaces and scalp. "In the presented study, the serum selenoprotein P level was significantly increased in patients with psoriasis compared with healthy persons." (PMID 32605214, 2020). "The presented study, for the first time, demonstrated the potential value of selenoprotein P as an additional marker of inflammation in patients with psoriasis." (PMID 32605214, 2020). "Considering the multidirectional relation between NAFLD and psoriasis, it is worth assessing the potency of selenoprotein P in that interplay." (PMID 32605214, 2020). "Elafin, clusterin, or selenoprotein P may act as biomarkers for psoriasis and comorbid metabolic diseases." (PMID 33804147, 2021). "Furthermore, we aimed to assess the impact of systemic antipsoriatic therapy on selenoprotein P levels in order to estimate its potency to evaluate the efficacy of methotrexate and acitretin in psoriasis or perhaps contribute to develop newer therapeutic paths." (PMID 32605214, 2020). "Selenoprotein P (SeP), a member of hepatokines, is involved in the development of various metabolic diseases closely related to psoriasis, but it has not been explored in that dermatosis so far." (PMID 32605214, 2020). "Besides the undoubted positive role of selenoprotein P in human organisms, it also has a negative influence on numerous processes and can be somehow be considered as a double-edged sword, probably in psoriasis as well." (PMID 32605214, 2020).
thyroid (2 papers, 2021 to 2022). "Besides these interrelated biomarkers of Se status, natural autoantibodies to SELENOP (SELENOP-aAb) have recently been reported in healthy subjects and thyroid patients, obviously capable of interfering with regular Se transport by SELENOP." (PMID 35636018, 2022). "However, a considerable fraction of thyroid patients express SELENOP-aAb to varying degrees, with some patients being highly positive for SELENOP-aAb." (PMID 34884891, 2021). "We hypothesized that natural autoantibodies to SELENOP are prevalent in thyroid patients, impair Se transport, and negatively affect GPX3 biosynthesis." (PMID 34884891, 2021).
thyrotoxicosis (2 papers, 2022). A hypermetabolic syndrome caused by the elevation of thyroid hormone levels in the serum. "In addition, copper and selenium homeostasis also played important role in innate immunity, and their transport proteins Ceruloplasmin (CP) and selenoprotein P (Sepp1) were downregulated in thyrotoxicosis mice." (PMID 35720307, 2022). "Selenoprotein P (Sepp1) plays a key role in selenium homeostasis and defense ability, and it was upregulated in the RSGB treatment group, which might be helpful to maintain the defense ability in thyrotoxicosis mice." (PMID 36389720, 2022).
alcoholic hepatitis (1 paper, 2021). Acute hepatitis resulting from ingestion of alcohol. "To date, various ethanol-responsive genes or altered genes in alcoholic hepatitis, including transcription factors, have been identified and may be responsible for alcohol-induced SELENOP expression in the liver." (PMID 33693023, 2021).
alcoholic liver cirrhosis (1 paper, 2021). A disorder of the liver characterized by the presence of fibrotic scar tissue instead of healthy liver tissue. "In contrast, binge alcohol consumption and alcoholic liver cirrhosis cause reduced serum selenium and selenoprotein P." (PMID 33693023, 2021).
alcoholism (1 paper, 2021). "Lower selenium levels may cause the reduced selenoprotein P levels observed in cases of alcoholism." (PMID 33693023, 2021).
amyloidosis (1 paper, 2022). A disorder characterized by the localized or diffuse accumulation of amyloid protein in various anatomic sites. "In the spline regression analyses between CSF neurodegeneration and amyloidosis biomarkers and CSF selenoprotein P levels, Aβ1-42 levels slightly and positively correlated with selenoprotein P in the AD group." (PMID 36077261, 2022).
anaemia (1 paper, 2025). "Anaemia and hypoxia may also affect selenoprotein expression patterns, and inversely, low Se and the selenium transporter SELENOP status are associated with anaemia in CVD." (PMID 40227412, 2025).
Azoospermia (1 paper, 2021). Absence of any measurable level of sperm,whereby spermatozoa cannot be observed even after centrifugation of the semen pellet. "Nevertheless, some causal links between specific selenoprotein deficiencies and phenotypes (e.g., abnormal thyroid function and deiodinase enzymes; low plasma Se and SELENOP, GPX3; azoospermia and SELENOV, GPX4, TXRND3; myopathy and SELENON) can be made." (PMID 34884733, 2021).
brain glioma (1 paper, 2022). A malignant glioma that involves the brain. "A pan-cancer expression analysis revealed the association of selenoprotein P (SELENOP) with a better prognosis in most cancers, but a poorer prognosis in brain glioma and uterine corpus endometrioid carcinoma." (PMID 35887320, 2022).
colon adenocarcinoma (1 paper, 2023). "Similarly, CRISPR activation–mediated (CRISPRa-mediated) SELENOP overexpression in RKO cells or MC38 (mouse colon adenocarcinoma) cells augmented WNT3A-induced TOPFlash activity." (PMID 37166989, 2023).
colorectal polyps (1 paper, 2023). "We next evaluated SELENOP expression in colorectal polyps and cancers." (PMID 37166989, 2023).
delirium (1 paper, 2026). A disorder characterized by confusion; inattentiveness; disorientation; illusions; hallucinations; agitation; and in some instances autonomic nervous system overactivity. "Other notable proteins robustly associated with delirium in our proteomic analysis are BCAN, SELENOP, AREG and MSLN." (PMID 41286463, 2026).
dry eye (1 paper, 2016). "Previously, we showed that selenium compounds, e.g., selenoprotein P and Se-lactoferrin, were candidates for treatment of dry eye." (PMID 27833152, 2016).
Endotoxemia (1 paper, 2020). "After 8 h of endotoxemia, plasma levels of Se and the Se transporter protein, SELENOP were significantly decreased." (PMID 33224150, 2020). "SELENOP is a Se enriched protein with 10 Se moieties, and we considered the possibility that hepatic Se is locally redirected for the induction of stress-related hepatic selenoenzymes after endotoxemia." (PMID 33224150, 2020).
Familial adenomatous polyposis (1 paper, 2023). Familial adenomatous polyposis (FAP) is characterized by the development of hundreds to thousands of adenomas in the rectum and colon during the second decade of life. "Similarly, in a single-nucleus RNA-Seq (snRNA-Seq) data set generated from patients with familial adenomatous polyposis (FAP) and from non-FAP patients, SELENOP expression was greater in adenocarcinomas than in polyps or unaffected stem cells." (PMID 37166989, 2023).
Hypoglycemia (1 paper, 2021). A decreased concentration of glucose in the blood. "The extent to which SELENOP-aAb may alter the protective interaction of Se and SELENOP on the vasculature is unknown, and the question of whether functional Se deficiency by low Se supply, in combination with SELENOP-aAb causes hypoglycemia needs to be investigated." (PMID 34884891, 2021).
Impaired glucose tolerance (1 paper, 2024). An abnormal resistance to glucose, i.e., a reduction in the ability to maintain glucose levels in the blood stream within normal limits following oral or intravenous administration of glucose. "Research suggests that selenoprotein P (SELENOP) produced by the liver can transport selenium to peripheral tissues, and that elevated serum SELENOP levels may result in decreased insulin sensitivity and impaired glucose tolerance." (PMID 39149550, 2024).
Infertility (1 paper, 2025). "Furthermore, there are just a few studies examining the effects of Se status or supplementation on outcomes of IVF and pregnancy, as well as the relationship between other functional Se-status biomarkers in seminal plasma (primarily GPX and selenoprotein P) and infertility." (PMID 41586246, 2025).
Intellectual disability (1 paper, 2022). "Significantly reduced SELENOP concentrations were found in association with intellectual disability (mean ± SD (standard deviation); 3.9 ± 0.9 mg/L vs. 4.4 ± 1.2 mg/L, p = 0.015)." (PMID 35745104, 2022).
invasive breast carcinoma (1 paper, 2022). A carcinoma that infiltrates the breast parenchyma. "In this manuscript, we describe the prognostic relevance of autoimmunity to the Se transporter SELENOP in patients with a new diagnosis of primary invasive breast cancer." (PMID 35636018, 2022).
ischemic stroke (1 paper, 2025). A stroke disorder caused by obstruction of blood flow to the brain, due to thrombotic (local blood clot formation) or embolic (due to a blood clot or other material traveling from another site) event. "Our present meta-analysis revealed that increased selenoprotein P and plasma/serum levels were linked to a decreased risk of ischemic stroke rather than whole blood." (PMID 41426996, 2025).
left ventricular hypertrophy (1 paper, 2023). Enlargement of the LEFT VENTRICLE of the heart. "Moreover, patients with SELENOP levels higher than the median had notably lower left atrium diameter and were less likely to develop left ventricular hypertrophy (p < 0.05)." (PMID 37371917, 2023).
liver fibrosis (1 paper, 2022). "In the study of liver fibrosis models, selenium levels were coherently down-regulated with expression levels of anti-oxidant factors such as selenoprotein P and GPX." (PMID 35745140, 2022).
lymph node metastasis (1 paper, 2025). "The expression of SELENOP was not statistically significant concerning patient age (p > 0.05); however, differences in histological grade, lymph node metastasis, LAG-3, CD244, estrogen receptors, progesterone receptors, and Her-2 expression were statistically significant (p < 0.05)." (PMID 40821907, 2025).
macular degeneration (1 paper, 2009). Loss of vision in the central portion of the retina (macula), secondary to retinal degeneration. "A protective effect of selenium in preventing macular degeneration has also been shown and another selenium transporter (selenoprotein P) has been found to be upregulated in the retina of chicks that were treated with either positive or negative lenses." (PMID 20019881, 2009).
malaria (1 paper, 2025). Malaria is a serious and sometimes fatal disease caused by a parasite that commonly infects a certain type of mosquito which feeds on humans. "In trypanosomes, malaria parasites, and schistosomes, thiol- and selenoproteins such as trypanothione reductase, tryparedoxin, glutathione peroxidase, selenoprotein P, and selenium-containing TrxRs have been identified as potential drug targets." (PMID 40804207, 2025).
male infertility (1 paper, 2018). The inability of the male to effect fertilization of an ovum after a specified period of unprotected intercourse. "Targeted genetic deletion of the Se transport protein, selenoprotein P (SELENOP) in mice results in male infertility, but female mice remain fertile." (PMID 29385050, 2018).
oophoritis (1 paper, 2025). Inflammation of the ovary, generally caused by an ascending infection of organisms from the endocervix. "Selenoproteins like glutathione peroxidases (GPx‐1, GPx‐3 and GPx‐4), selenoprotein P (SELENOP), and selenoprotein S (SELENOS) play a crucial role in sperm development, maturation, protection of ovarian follicles, and regulating oophoritis and placentitis." (PMID 41268629, 2025).
ovarian carcinoma (1 paper, 2023). A malignant neoplasm originating from the surface ovarian epithelium. "Lastly, we monitored the expression of GPX1, GPX4, and SELENOP genes in patients with ovarian cancer using the publicly available Oncomine database to elucidate the clinical significance of GPx4 in ovarian cancer." (PMID 36768241, 2023). "Oncomine revealed that the mRNA levels of GPx1 and GPx4 were strongly elevated in ovarian cancer tissues compared to those in normal ovarian tissues, whereas SELENOP levels were decreased in ovarian cancer tissues." (PMID 36768241, 2023).
phacomatosis (1 paper, 2022). "In direct comparison to the other patients, the children with phacomatosis displayed a tendency of Se deficiency, with a slightly lower serum Se and SELENOP status." (PMID 35745104, 2022).
pneumonia (1 paper, 2020). An acute, acute and chronic, or chronic inflammation focally or diffusely affecting the lung parenchyma, caused by an infection in one or both of the lungs (by bacteria, viruses, fungi, or mycoplasma.). "Circulating levels of Se and the Se enriched transporter protein selenoprotein P (SELENOP) decrease in septic and critically ill adults, and are inversely correlated with the risk of multiorgan dysfunction, pneumonia, and death." (PMID 33224150, 2020).
prediabetes (1 paper, 2025). "Clinical evidence further supports this duality: serum SELENOP levels increase during prediabetes but decline as T2DM progresses, suggesting compensatory overexpression preceding selenoprotein exhaustion." (PMID 40416378, 2025).
protein misfolding disease (1 paper, 2024). "In our case series, glutathione peroxidase, selenoprotein P, and selenoprotein M were excreted in urine of cats with renal AA amyloidosis in larger amounts, suggesting a link between oxidative damage and the protein misfolding disease." (PMID 37991136, 2024).
rhabdomyosarcoma (1 paper, 2021). A rare aggressive malignant mesenchymal neoplasm arising from skeletal muscle. "Human embryo rhabdomyosarcoma RD cells express both ApoER2 and LRP1, which show low affinity for SELENOP uptake, and high amount of SELENOP is necessary for the uptake and use of Se in SELENOP." (PMID 34124127, 2021).
Wilson disease (1 paper, 2023). A very rare inherited multisystemic disease presenting non-specific neurological, hepatic, psychiatric or osseo-muscular manifestations due to excessive copper deposition in the body. "Accordingly, SELENOP levels are relatively low in serum of patients with Wilson’s disease and LPP rats, especially in those with low CP concentrations." (PMID 37311819, 2023). "Accordingly, SELENOP levels were low in serum of Wilson’s disease patients and Wilson’s rats." (PMID 37311819, 2023). "From the Wilson’s disease samples (rat and human), we can conclude that a low serum copper concentration is positively correlated with low circulating SELENOP levels (humans: Pearson’s r = 0.425; p-value = 0.07) which is supposed to be caused by hepatic copper accumulation." (PMID 37311819, 2023).
cancer (55 papers, 2006 to 2026). A tumor composed of atypical neoplastic, often pleomorphic cells that invade other tissues. "SELENOP polymorphisms in the DNA from various cancer types have also been associated with cancer risk and patient mortality." (PMID 41563517, 2026). "In the intrinsic view, KLK6-positive cells showed increased proximity to cancer-associated fibroblasts (myCAF, iCAF), plasma cells, SELENOP+ macrophages, SPP1+ macrophages, MK167+ macrophages, and endothelial cells." (PMID 41383634, 2025). "A central component to the interaction between selenium and selenoprotein synthesis, and presumably to cancer risk, is SELENOP, which delivers selenium to tissues." (PMID 32806741, 2020). "In the case of colorectal cancer, the SELENOP genotype was reported to interact with selenium status to impact selenoprotein levels and cancer risk." (PMID 32806741, 2020). "These include key biological stress response genes like GPXs, TXNRD3, SELENOS, SELENOH, and the related SOD2 gene implicated in cancer cell survival, and genes such as SELENOP and SEPHS2 involved in Se biosynthesis." (PMID 30469315, 2018). "Furthermore, low SELENOP levels are linked to an increased risk of developing cancers, including those of the kidney, colon, esophagus, and lungs." (PMID 39942544, 2025). "This may be consistent with SELENOP's role in protecting cells from oxidative damage by neutralizing free radicals, thus reducing cancer risk." (PMID 40821907, 2025). "Despite the lack of experimental evidence, it is possible to hypothesize that the increased SELENOP in M2 macrophages may offset the loss of SELENOP in cancer cells and support metastasis by supplying it in a paracrine manner." (PMID 32426284, 2020). "Given the functionality of the SELENOP variations and the impact of selenium availability on selenoprotein synthesis, there have been several studies investigating the associations between SELENOP variations and cancer risk." (PMID 32806741, 2020). "Recent research into the mechanisms by which cancer cells resist ferroptosis has shown that SELENOP, acting as a regulatable selenium source within cancer cells, can be internalized by cells via the receptor LRP8 and subsequently degraded within lysosomes." (PMID 41323827, 2025). "A decrease in SELENOP levels has been associated with resistance to chemoradiotherapy (CCRT) in cervical cancer, highlighting its potential as a modulator of cancer therapy sensitivity through lipid metabolism regulation." (PMID 39942544, 2025). "Selenoproteins, particularly GPx1, GPx3, TrxR, SELENOP, SELENOM, SELENOS, SPS1, and SPS2, are essential in regulating oxidative stress and cancer risk." (PMID 39942544, 2025). "Selenium and its biomarker, selenoprotein P (SEPP1), have been implicated in health, including cancer prevention, neurological function, and dopamine signaling." (PMID 38793071, 2024). "Significant variations in SELENOP expression levels were observed among specific subgroups, particularly across different cancer grades and demographic categories, highlighting its nuanced role in HCC pathogenesis." (PMID 39001444, 2024). "Findings indicate that selenoprotein P expression varies significantly with cancer stage and patient demographics like race and gender." (PMID 39001444, 2024). "The multifaceted nature of SELENOP in cancer encompasses both selenium transport and antioxidant functions." (PMID 39001444, 2024). "When we integrated this data set with its corresponding patient-matched normal tissue data sets, we observed increases in SELENOP expression from normal crypt stem cells to ASCs to MSS cancer cells." (PMID 37166989, 2023). "We show here that selenium/selenocysteine can be obtained by cancer cells via multiple routes: First by the SELENOP/LRP8 axis and second, via the activity of system Xc− (SLC7A11/SLC3A2)." (PMID 37435859, 2023).